PPP1R3E (protein phosphatase 1 regulatory subunit 3E)
Description:
Acts as a glycogen-targeting subunit for PP1. PP1 is involved in glycogen metabolism and contributes to the activation of glycogen synthase leading to an increase in glycogen synthesis.
Synonyms: FLJ00089
Tractability: No criterion of Open Targets' tractability assessment is met for any kind of drug.
Gene: Protein-coding gene on chromosome 14 (23,295,652 to 23,302,908, reverse strand). Ensembl gene ENSG00000235194.
Subcellular location (Human Protein Atlas): Microtubules; Mitochondria; Mitotic spindle
Gene Ontology:
Molecular function: [phosphorylase] phosphatase activity; glycogen binding; protein phosphatase 1 binding; phosphoprotein phosphatase activity
Biological process: positive regulation of glycogen biosynthetic process; regulation of glycogen biosynthetic process
Cellular component: glycogen granule; protein phosphatase type 1 complex
Genetic constraint (gnomAD): Loss-of-function variants: 20 observed, 12.12 expected, observed/expected ratio (o/e) 1.65, 90% interval 1.12 to 1.95. The synonymous counts are far from expectation, so gnomAD's model fits this gene poorly and the ratio says little. Missense variants: 498 observed, 338.4 expected, observed/expected ratio (o/e) 1.47, 90% interval 1.37 to 1.59. Synonymous variants: 208 observed, 139.9 expected, observed/expected ratio (o/e) 1.49, 90% interval 1.33 to 1.67.
Homologues: Orthologues: macaque PPP1R3E (98% identical), chimpanzee PPP1R3E (98% identical), dog PPP1R3E (96% identical), pig PPP1R3E (95% identical), rabbit PPP1R3E (94% identical), guinea pig PPP1R3E (93% identical), mouse Ppp1r3e (90% identical), tropical clawed frog ppp1r3e (47% identical). Paralogues in human: PPP1R3D (35% identical), PPP1R3G (31% identical), PPP1R3F (26% identical), PPP1R3A (24% identical), PPP1R3B (20% identical), PPP1R3C (19% identical).
Diseases named in the same sentence as PPP1R3E in open-access papers:
PPP1R3E is named in the same sentence as 1 disease in open-access papers, as found by Europe PMC text mining. Sharing a sentence is not in itself a finding about the gene and the disease. The quoted sentences say what the papers report.
Insulin resistance (2 papers, 2020 to 2025). Increased resistance towards insulin, that is, diminished effectiveness of insulin in reducing blood glucose levels. "Insulin resistance (ko04931) is closely related to glucose metabolism and was associated with certain DEGs and DAMs, such as Pygm, Ppp1r3e, D-glucose-6-phosphate, D-fructose-6-phosphate, and UDP-N-acetylglucosamine." (PMID 41035051, 2025). "The samples from the carotid sheath showed an enriched expression of genes described to play a role in insulin resistance (PPP1R3E, PRKCQ, PRKCZ, CPT1B, MGEA5, RPS6KB2, OGT; KEGG_PATHWAY hsa04931:Insulin resistance)." (PMID 32661330, 2020).